BCL2 (BCL2 apoptosis regulator)
Diseases named in the same sentence as BCL2 in open-access papers (continued):
Sharing a sentence is not in itself a finding about the gene and the disease.
tumor (continued). "The reduction of the Bcl‐2/Bax ratio induces mitochondrial membrane damage of tumor cells, leading to the massive release of Cytochrome C and ultimately enhancing the expression and activity of Caspase‐3." (PMID 40497373, 2025). "A study has reported that THC can diminish the expression of Bcl-2/Bax proteins, thereby triggering the apoptosis of tumor cells." (PMID 40332041, 2025). "This activation promotes the expression of the anti-apoptotic protein Bcl-2 in tumor cells, enhancing their resistance to apoptosis and thereby facilitating tumor progression." (PMID 41346580, 2025). "miR-34a exerts its tumor suppressor function by targeting key oncogenic regulators such as cyclin D1, BCL-2, SIRT1, and CDK6, which are involved in cell proliferation and survival." (PMID 40429954, 2025). "The nanosystem demonstrated sustained drug release and enhanced uptake by A549 cells, leading to increased cytotoxicity, inhibition of tumor cell migration, and promotion of apoptosis by the regulation of Bcl-2, Bax, and Caspase-3 expression." (PMID 41471822, 2025). "The results showed that Chaetocin upregulated the levels of Bax, Caspase-3/9, ROS, JNK and downregulated the expression of Bcl-2 to promote apoptosis to inhibit the tumor volume and weight and to improve the sensitivity of 5-FU drug." (PMID 40342991, 2025). "These compounds exert direct anti-tumor effects by inhibiting tumor cell proliferation through blocking topoisomerase I activity, regulating the caspase-3/Bcl-2 pathway to induce apoptosis, and suppressing angiogenesis." (PMID 41320762, 2025). "Noteworthily, BCL2 family proteins play a key role in tumorigenesis and progression, and pharmacological inhibition or knockdown of BCL2 enhances the antigen-presenting capacity of dendritic cells while simultaneously optimizing tumor immunosurveillance." (PMID 39995416, 2025). "In KoRV-infected koalas with neoplasia, Bcl-2 expression was significantly upregulated, particularly in those infected with multiple KoRV subtypes." (PMID 41305531, 2025). "Studies suggest that LIN28B promotes cell survival and tumorigenesis by increasing BCL-2 expression and inhibiting apoptosis, indicating a potential influence on the tumor microenvironment (TME)." (PMID 40746360, 2025). "Subsequently, CPP-mediated potent membrane penetration enhanced the cellular uptake of siBcl-2 in HepG2 cells, leading to the substantial downregulation of Bcl-2 levels, effectively suppressing tumor progression." (PMID 40756358, 2025). "Results showed that upon cytokine stimulation most of the studied genes were expressed at a lower level in the tumor cells than in control cells, such as Stat1, Irf1, Cxcl9, Cxcl10, IκBα, and Bcl2 (p< 0.05)." (PMID 40287766, 2025). "Various studies revealed that Bcl-2 played a critical role in apoptosis and the anti-tumor pathway mediated by PTX, and the low expression of Bcl-2 was the key to apoptosis and the anti-tumor effect mediated by PTX." (PMID 41315221, 2025). "The existing literature supports the strategy of inducing apoptosis of tumor cells by regulating the expression of Bcl-2." (PMID 40507857, 2025). "Constitutive NF-κB activation in tumor cells increases the expression of prosurvival genes (e.g., BCL2, XIAP), angiogenic factors (VEGF, IL-8), and metastasis-promoting molecules (CXCR4, MMPs)." (PMID 40562870, 2025).
tumor (continued). "The results showed that AS-IV dose-dependently inhibited the proliferation of CRC cells and suppressed tumor growth, activated the levels of Caspase-3/7/9, Bax, inhibited the expression of Bcl-2, and promoted the cell cycle arrest at G0 phase." (PMID 40342991, 2025). "BH3 profiling has been utilized for defining the dependence of tumor cells on a specific pro-survival BCL2 protein or a combination of them." (PMID 40204951, 2025). "Additional mechanistic studies at the protein level, including Western blotting of Bax, Bcl-2, NF-κB, and caspases, as well as immunohistochemistry in tumor tissues, would provide stronger molecular evidence." (PMID 41155667, 2025). "The Mantel–Cox test indicated significance in histological subtype (p = 0.006), tumor stage (p = 0.002), ER (p = 0.020), BCL2 (p = 0.041), and age over 65 years (p ≤ 0.001)." (PMID 40243780, 2025). "The downregulation of Bcl-2 levels coupled with elevated Bax expression is known to enhance tumor cell apoptosis in response to various external stimuli." (PMID 40136409, 2025). "The elevated expression of the Bcl-2 protein in tumor cells, compared to normal cells, indicates that inhibitors targeting this protein have minimal impact on normal cells." (PMID 39863836, 2025). "GCP modulates the expression of tumor-related genes such as Bcl-2 and Bax, thereby inducing apoptosis in tumor cells and inhibiting tumor formation and growth." (PMID 40462156, 2025). "Conventional double-color FISH confirmed that all tumor cells carried gene rearrangements of BCL2 and MYC." (PMID 41142614, 2025). "Further tumor tissue analysis revealed that B. breve-IL24 treatment led to decreased expression of the anti-apoptotic protein BCL-2 and increased expression of the pro-apoptotic protein Bim, supporting its role in promoting tumor cell apoptosis." (PMID 40805186, 2025). "The size and weight of the tumor, as well as the expressions of P-gp, Survivin, Bcl-2, p-Akt and p-PI3K genes, were also measured." (PMID 38243937, 2025). "Recently, a research team developed a magnetothermal-activated CRISPR-Cas9 gene-editing system to target the HSP70 and BCL2 genes in tumor cells." (PMID 40297581, 2025). "A role of miR-150-5p/myb interference in CRC tumor growth has been demonstrated previously in nude mice; however, the tumor suppressor role of miR-150-5p mediated via bcl2 and cry1 expression needs to be addressed in the next studies." (PMID 40868120, 2025). "The TCGA database revealed that CASP3 expression in PCa tumor samples was elevated relative to normal tissues (p < 0.05), whereas BCL2 was downregulated in PCa tumors (p < 0.05)." (PMID 40344485, 2025). "It activates the BCL2 gene to inhibit tumor cell apoptosis and also activates the Wnt/β-catenin pathway, promoting initiation, progression, invasion and cell metastasis." (PMID 41465470, 2025). "IHC analysis of the anti-apoptotic marker (BCL-2) declared that the percentages of BCL-2-immunostained tumor cells (red arrows) in FeO NPs-DE-treated and Gem-treated mice were 37.6 ± 0.75% and 80.6 ± 0.55%, respectively, relative to the PBS-treated group." (PMID 39888413, 2025). "Low doses of LNT decreased the protein levels of Nur77 but promoted those of Bcl-2 in tumor tissues compared to those in the control tissues." (PMID 39744474, 2025). "In recent years, it has also been demonstrated that the balance of the anti‐apoptotic proteins Bcl‐2 and Bcl‐xl and pro‐apoptotic proteins Bax and Bad in the endogenous apoptotic pathway plays an important role in tumor cell survival after radiation." (PMID 41287826, 2025).
tumor (continued). "Studies have confirmed that transfection of lncRNA NEAT1 small interfering RNA (siRNA) to hepatoma cell HepG2, down-regulation of lncRNA NEAT1 expression, can inhibit the expression of EGFR and Bcl-2, thereby inhibiting tumor cell proliferation and invasion." (PMID 41186893, 2025). "Immunofluorescence showed the highest KI67 and BCL2 fluorescence intensity in tumour tissues from the ZNF468 overexpression group." (PMID 40702875, 2025). "Bcl-2’s overexpression and phosphorylation play a vital role in regulating cell proliferation, contributing significantly to tumor growth and multidrug resistance in HCC." (PMID 40841912, 2025). "In independent clinical cohorts, where RASAL2 was elevated in TNBC tumours post-treatment, BCL2 was also significantly elevated post-treatment." (PMID 39890967, 2025). "The pathogenesis of THRLBCL involves several genetic alterations also seen in DLBCL, including overexpression of BCL2 and mutations in TNFAIP3 and MYD88 (L265P), which promote tumor cell survival." (PMID 41141099, 2025). "We also showed that Bcl-2 is overexpressed in tumor B cells and in the peri-T M1 macrophage compartment." (PMID 41415285, 2025). "This concerted dysregulation culminated in a dose-responsive decline of the Bcl-2/Bax ratio, functionally demonstrating enhanced tumor cell apoptosis through mitochondrial pathway activation." (PMID 40839202, 2025). "Vehicle-treated tumor-bearing mice served as the control group, while Brusatol-treated mice showed markedly reduced Nrf2, BCL-2, Ki67, and KRAS expression in metastatic liver nodules." (PMID 41212415, 2025). "GPR65 KO tumors expressed increased TFs of the AP-1 family (Fos and Fosb) and the antiapoptotic marker Bcl2, known to promote tumor cell survival." (PMID 39998425, 2025). "miR-15a directly targets and negatively regulates anti-apoptotic genes like BCL2L2 and BCL2, as well as Smad3, thereby suppressing tumour progression and metastasis." (PMID 40978098, 2025). "While this work undermines the prospects of Bcl-2 rG4 as an anti-tumor therapy target, it raised important questions about the adequacy of primary DLR and in vitro translation methods for assessing rG4’s influence on translation efficiency." (PMID 39940956, 2025). "Mechanistically, compared to IL-2 treatment, Neo-2/15 stimulation significantly reduced the levels of the pro-apoptotic proteins Bax and Bak, and increased the levels of the anti-apoptotic molecules Bcl-2 and Bcl-xl in BBζ co-cultured with tumor cells." (PMID 40025022, 2025). "BTK has an important role in the activation of the B-cell receptor (BCR)-signaling pathway while the anti-apoptotic BCL-2 protein is overexpressed in tumor cells." (PMID 40864758, 2025). "Most importantly, BCL-2 is a target of several anticancer agents to curb tumor growth through intrinsic apoptosis." (PMID 40301461, 2025). "The effect of the four tested treatment groups was evaluated on the key apoptotic protein markers (BAX, BCL-2, and caspase 3,7, 8, and) 9 which are vital for stopping tumor progression and the activation of the intrinsic and/or extrinsic apoptotic pathways." (PMID 40218923, 2025). "After 4 weeks of treatment, sulindac treatment significantly reduced tumor growth, improved the inflammatory state in KpB mice, and decreased the expression of Ki-67, Cox-2 and Bcl-2 in OC tissues." (PMID 40371356, 2025). "This study does not include in vivo functional validation of miR-150-5p’s effect on myb, bcl2, and cry1 expression or tumor growth." (PMID 40868120, 2025). "APG-2575 rapidly penetrates tumor cells and disrupts the Bcl-2–Bim complex, ultimately inducing Bax/Bak-dependent, caspase-mediated apoptosis, and demonstrating potent antitumor activity." (PMID 40949156, 2025). "In multiple tumour contexts, low SHBG states are associated with increased c-Myc and Bcl-2 expression and activity, upregulation of glycolytic effectors GLUT1, LDH and HK2, promoting mitochondrial resistance to apoptosis." (PMID 41586225, 2025).
tumor (continued). "Evidence suggests that scaRNA2 contributes to tumor proliferation by fostering the expression of Bcl-2 and EGFR." (PMID 41276852, 2025). "Further molecular studies are needed to elucidate the different implications and/or interactions of SYT::SSX1/2/4 and the role of BCL-2 in SS tumor onset and growth." (PMID 40416104, 2025). "Apoptosis is the core mechanism of action for anti-tumor drugs, and its regulation depends on the balance between pro-apoptotic factors (Bax, Caspase-3) and anti-apoptotic factors (Bcl-2)." (PMID 40432889, 2025). "This dual-action mechanism markedly enhanced Bcl-2 silencing efficiency, downregulating the Bcl-2 expression levels in tumor tissues to 0.22." (PMID 40756358, 2025). "lncRNAs, such as HOTAIR and MALAT1, upregulate BCL-2 via epigenetic and ceRNA mechanisms, promoting tumor survival." (PMID 41020820, 2025). "In many cancers, NF-κB is constitutively activated, enabling tumor cells to evade apoptosis through upregulation of anti-apoptotic genes like Bcl-2 and IAPs." (PMID 40572628, 2025). "Immunoblotting analyses showed that the CSNK1D expression levels were correlated with the levels of E-cadherin, N-cadherin, Vimentin, BCL2, and Bax in the tumor tissues of nude mice." (PMID 41353440, 2025). "In leukemia and breast cancer CSCs, overexpression of BCL-2 and BCL-XL has been associated with resistance to chemotherapy, enabling CSCs to evade apoptosis and sustain tumor progression." (PMID 40608151, 2025). "Tumour cells bearing the IGH::BCL2 translocation are more dependent on BCL2 for survival and are more sensitive to BCL2 inhibitors." (PMID 40356256, 2025). "A similar downregulation pattern was observed in both CVID and CLL with SID groups for miR-15a-5p and miR-29a-5p, which are known tumor suppressors involved in regulating BCL2 expression and lymphocyte survival." (PMID 41148792, 2025). "VPA increases the expression of genes involved in tumor differentiation and progression that are regulated by the ERK-AP-1 pathway, including growth-associated protein-43 (GAP-43) and Bcl-2." (PMID 40722968, 2025). "Navitoclax, a BCL-2 inhibitor, clears chemotherapy-induced senescent cells and synergizes with PD-1 inhibitors to boost tumor remission rates." (PMID 40510156, 2025). "Accordingly, previous studies have found that BCL2 is subjected to strong miRNA and TF regulation in vitro, in tumour samples, and in animal models." (PMID 40041206, 2025). "Bcl-2 expression was significantly lower in the CD68+ macrophage compartment compared with the CD20+ tumor cell compartment, but was correlated with M1 (CD86+) macrophage infiltration." (PMID 41415285, 2025). "In vitro experiments have shown that BCL2 inhibitor AT-101 can reduce tumor cell proliferation and enhance the apoptotic effect of docetaxel." (PMID 39735667, 2025). "The expression levels of Bcl2 and Puma in tumor tissues from different groups of mice were assessed using IHC." (PMID 40109863, 2025). "miR365 has been recognized as a prominent anticancer target, as it can act as tumor suppression gene by downregulating the expression of Bcl2 and Ki67." (PMID 40708975, 2025). "Simvastatin induces apoptosis in tumor cells by upregulating Bax and downregulating Bcl-2 expression." (PMID 40140647, 2025). "Immunohistochemical (IHC) staining using antibodies specific for the proliferation marker (Ki-67) and apoptosis markers (BCL-2) further validated the inhibitory effect of circ_0001766 on tumor progression." (PMID 40263288, 2025).
tumor (continued). "In contrast, the inclusion of a BCL2 inhibitor significantly promoted tumor cell death and inhibited tumor growth." (PMID 39995416, 2025). "This reciprocal modulation of Bax/Caspase-3 activation and Bcl-2 suppression confirms that RES-PNPs potentiate apoptotic signaling within tumor cells more effectively than free RES." (PMID 41301523, 2025). "On the other hand, it suppresses the expression of pro-apoptotic proteins such as Bax while activating anti-apoptotic proteins such as Bcl-2, thereby inhibiting cell apoptosis and creating a favorable environment for the growth and survival of tumor cells." (PMID 40430234, 2025). "Immunohistochemical staining also indicated that the expression of Nur77 was significantly downregulated, whereas that of Bcl-2 was significantly increased after treatment with LNT in tumor tissues." (PMID 39744474, 2025). "The miR-34a is a key regulator of tumor suppression controlling the expression of several targets involved in the cell cycle (c-MYC, E2F, CDK4 and CDK6), apoptosis (BCL2 and SIRT1) and tumor-associated invasion (c-MET)." (PMID 40755967, 2025). "Overexpression of Bcl-2 is widely considered to contribute to the occurrence and development of tumors, and even enhance the migratory ability of tumor cells." (PMID 40507857, 2025). "Inappropriate overexpression of the apoptosis-suppressing Bcl-2 protein has been shown to contribute to tumorigenesis in various tumor types." (PMID 38713435, 2025). "Apoptosis family proteins, such as Bcl-2, work by neutralizing pro-apoptotic proteins like Bax, which protects the tumor cells from apoptosis by occurring in the cytosol and then translocating to the mitochondria to induce apoptosis." (PMID 40097629, 2025). "The protein expression levels of Bax and Bcl-2 in the tumor tissues of nude mice were measured by Western blot." (PMID 40076586, 2025). "Venetoclax, also known by its names ABT-199, Venclexta, and Venclyxto, is an orally administered, highly selective BCL2 inhibitor capable of triggering tumor cell apoptosis." (PMID 39735667, 2025). "Our case indicates that VEN, as a BCL-2 inhibitor, has its unique anti-tumor effects and holds promise to become an effective treatment option for patients with relapsed/refractory APL." (PMID 41398814, 2025). "BCL plays a crucial role in the proliferation and division of ATRT, BCL-2 inhibitors have significant effects on different tumor cell clusters in different ATRT subtypes." (PMID 41148473, 2025). "Consistent with our earlier reported observations, enhanced tumor cell death was validated by the significantly increased Bax/Bcl2 ratio in tumor tissue of Myr-NE xenografts, compared to Myricetin treated xenografts." (PMID 40552278, 2025). "PIC can inhibit the phosphorylation activity of Beclin-1 and hinder its binding with Bcl-2, further triggering Beclin-1-dependent autophagic signaling activation, effectively suppressing tumor progression in GC xenograft models and inducing cell apoptosis." (PMID 40066330, 2025). "An increase in the expression of proapoptotic proteins (such as Bax) and a reduction of antiapoptotic proteins (such as Bcl‐2) have been observed in tumor models treated with PDT, confirming this apoptotic profile." (PMID 40916083, 2025). "The Bcl‐2/Bax signaling pathway and Caspase‐dependent apoptosis pathway play an important role in promoting the occurrence and development of tumor cells." (PMID 40497373, 2025).